SNORD3B-2 (small nucleolar RNA, C/D box 3B-2)
Synonyms: U3-2B; U3b2
Gene: Small nucleolar RNA gene on chromosome 17 (19,063,346 to 19,064,136, reverse strand). Ensembl gene ENSG00000262074.
Gene Ontology:
Biological process: RNA processing
Cellular component: nucleolus
Diseases named in the same sentence as SNORD3B-2 in open-access papers:
SNORD3B-2 is named in the same sentence as 1 disease in open-access papers, as found by Europe PMC text mining. Sharing a sentence is not in itself a finding about the gene and the disease. The quoted sentences say what the papers report.
immune dysfunction (1 paper, 2022). "The dysregulation of U3 small nucleolar ribonucleoproteins genes (SNORD3B-1, SNORD3A, SNORD3B-2, SNORD3C, and SNORD3D) are related to age-related immune dysfunction, G0/G1 to S phase transition, oxidative-/ER-stress (23349890), and pathogenesis of AD." (PMID 35958988, 2022).